MIR3670-1 (microRNA 3670-1)
Synonyms: hsa-mir-3670; MIR3670; hsa-mir-3670-1
Gene: MicroRNA gene on chromosome 16 (14,907,717 to 14,907,781, forward strand). Ensembl gene ENSG00000263918.
Homologues: Paralogues in human: MIR3670-2 (100% identical), MIR3670-3 (100% identical), MIR3670-4 (100% identical).